RNU6-1090P (RNA, U6 small nuclear 1090, pseudogene)
Gene: Small nuclear RNA gene on chromosome 10 (116,538,183 to 116,538,276, forward strand). Ensembl gene ENSG00000200935.
Homologues: Orthologues: chimpanzee U6 (99% identical), macaque U6 (90% identical). Paralogues in human: RNU6-144P (82% identical), RNU6-333P (82% identical), RNU6-373P (82% identical), RNU6-98P (82% identical), RNU6-106P (81% identical), RNU6-1084P (81% identical), RNU6-1316P (81% identical), RNU6-14P (81% identical), RNU6-16P (81% identical), RNU6-181P (81% identical), RNU6-338P (81% identical), RNU6-434P (81% identical), and 1286 more.